LINC01976 (long independently transcribed non-coding RNA 1976)
Gene: Long non-coding RNA gene on chromosome 17 (43,926,845 to 43,950,464, forward strand). Ensembl gene ENSG00000261514.
Diseases named in the same sentence as LINC01976 in open-access papers:
LINC01976 is named in the same sentence as 1 disease in open-access papers, as found by Europe PMC text mining. Sharing a sentence is not in itself a finding about the gene and the disease. The quoted sentences say what the papers report.
osteosarcoma (1 paper, 2021). A usually aggressive malignant bone-forming mesenchymal neoplasm, predominantly affecting adolescents and young adults. "Cox regression analysis showed that AL133523.1, AC079760.2, and LINC01976 were independent prognostic factors for osteosarcoma." (PMID 34692688, 2021). "High expression of AP000943.1, AC015795.1, AC016746.1, LINC01976, and SNHG6 was not conducive to the prognosis of osteosarcoma." (PMID 34692688, 2021).